HNF1B (HNF1 homeobox B)
Diseases named in the same sentence as HNF1B in open-access papers (continued):
Sharing a sentence is not in itself a finding about the gene and the disease.
cancer (continued). "Moreover, recent research has revealed that expression HNF1B high promotes dedifferentiation to cancer stem cells via activation of the Notch pathway, and that HNF1B enhances invasive potential and the epithelial-mesenchymal transition (EMT) in cancer cells." (PMID 31366141, 2019). "Thus, a biological role(s) of HNF-1B as well as the significance of its aberrant cytoplasmic and membranous expressions in different types of cancer needs to be investigated in the future." (PMID 30065837, 2018). "We investigated the protein expression pattern of HNF-1B in 127 primary PDACs, 47 biliary adenocarcinomas, 17 metastatic PDACs, and 231 other common carcinomas that may mimic PDAC." (PMID 30065837, 2018). "To determine whether HNF1B expression can act as a brake on cancer development, we assessed the phenotypic effects of ectopic HNF1B over-expression in cancer cells, and observed a reversal of epithelial-to-mesenchymal transition (EMT)." (PMID 27732966, 2016). "Our functional and bioinformatic analyses support this, and suggest that candidates associated with these processes in particular may be relevant to the effects of HNF1B in a cancer context." (PMID 27732966, 2016). "The Chk1 inhibitor might be a novel target for developing cancer therapeutics in the HNF1β positive cells." (PMID 26464794, 2015). "Additionally, a genome-wide screen of RNAi data generated for ∼100 cell lines identified HNF1B as a major oncogene required for cancer cell survival." (PMID 25378557, 2015). "In this article, we review the relevance and significance of cancer-specific metabolism and how they are associated with biological characteristics of OCCC via expression of HNF1β, along with future clinical implications of targeting cancer-specific metabolism." (PMID 26375553, 2015). "The pathway with which HNF1β is involved in cancer is less understood." (PMID 26464794, 2015). "However, fine-mapping studies have revealed a complex genetic architecture at the HNF1B locus, demonstrated by lead SNPs and the direction of genetic effects being inconsistent between cancer types." (PMID 25378557, 2015). "Undifferentiated carcinomas showed expression of HNF-1β in 2/14 cases (14.3%)." (PMID 25884453, 2015). "Additionally, we divided patients into a low HNF1B expression group and a high HNF1B expression group, and CD8+ T cell, CD4+ T cell and B-cell levels were distinctly associated with overall survival of cancer patients in the different groups." (PMID 33173410, 2020). "In our study, the highest expression of HNF1B was observed in the subset of papRCC followed by ccRCC, despite the striking differences in the hypothesized origin and pathogenesis of these two types of cancers." (PMID 33051485, 2020). "Thus, targeting HNF1B for cancer therapy may have severe side effects, and targeting downstream targets of HNF1B may be required." (PMID 26910837, 2016). "However, precise mechanism how HNF1β contributes cancer biology remains to be elucidated." (PMID 26318292, 2015). "Patients were categorized into low and high HNF1B expression groups based on the CD4+ T cell, CD8+ T cell along with B‐cell levels, which were further grouped based on overall survival of cancer patients into different subsets." (PMID 33580750, 2021). "For instance, HNF1B expression is correlated with the infiltration grades of B cells, CD8+ T cells, CD4+ T cells, macrophages, neutrophils along with Dendritic cells in cancer." (PMID 33580750, 2021). "The results demonstrated a strong positive correlation between HNF1B expression and the infiltration levels of B cells, CD8+ T cells, CD4+ T cells, macrophages, neutrophils and DCs in cancer." (PMID 33173410, 2020). "However, the precise mechanism of how HNF1β contributes to cancer biology remains unclear." (PMID 26375553, 2015). "This might explain why HNF-1B showed variable nuclear, cytoplasmic and/or membranous staining patterns in PDAC and other carcinomas." (PMID 30065837, 2018).
cancer (continued). "Interestingly, we found that FXYD2 expression was positively correlated with the expression of a transcription factor, hepatocyte nuclear factor 1 homeobox B (HNF1B), in OCCC clinical specimens and cancer cell lines." (PMID 26910837, 2016). "A significantly larger proportion of the 67 CCC cases (82%) was positive for HNF1B immunostaining, whereas the other cancer types with the exception of four MC cases were all negative for HNF1B (p<0.0001)." (PMID 27340867, 2016). "Although facilitated lactic acid accumulation by lactic acid transporter MCTs (Monocarboxylate Transporters) was reported in some cancers, the expression of lactic acid import transporter MCT1 was low, and the lactic acid export transporter MCT4 was high in HNF1β-high cells." (PMID 26318292, 2015). "HNF1B (also known as TCF2) is a member of the homeodomain-containing transcription factors, a superfamily with diverse roles in development and often deregulated in cancer." (PMID 24040285, 2013). "Although some levels of methylation could be detected in normal tissues, methylation of HOXB13, HNF1B, and CGI 7:48 CpG islands was clearly more pronounced in intraductal carcinomas." (PMID 19250546, 2009). "Upon genotoxic stress, HNF-1β prevents Claspin ubiquitin-mediated proteasomal degradation through the action of USP28, therefore promoting Claspin stabilization, and inducing Chk1 activation and G2 cell cycle arrest, which provides cancer cells more time to repair DNA damage and survive." (PMID 41009395, 2025). "Previous studies have demonstrated that HNF-1β regulates the gene/protein expression such as annexin A4, osteopontin, uridine diphosphate (UDP)-glucuronosyl transferase 1A1 (UGT1A1), and insulin-like growth factor-binding protein 1 (IGFBP-1), which are vital for cancer progression." (PMID 34659566, 2021). "Due to the essential role of HNF-1B in pancreatic development, we hypothesized that HNF-1B was expressed in all cancers arising from the pancreatic ductal epithelium regardless of the histomorphology, and its expression may serve as a diagnostic marker of these cancers." (PMID 30065837, 2018). "We did not identify any correlations of total gene expression with cancer status for the JAZF1, MSMB, HNF1B, MYEOV or CTBP2 genes." (PMID 20569440, 2010). "Briefly, the expression of HNF1B and ECI2 mRNA was not statistically significantly different between the carcinoma and hyperplasia group (HNF1B: U = 278.0, Z = 1.51, p = 0.131; ECI2: U = 261.0, Z = 1.77, p = 0.078), although both genes showed a lower expression in AH." (PMID 32873863, 2020).
kidney disease (73 papers, 2013 to 2026). "Overall, these data implicate cluster 5 cells in kidney deregulation, as HNF1B mutations are associated with kidney diseases and EGFR plays a major role in the development of kidney fibrosis." (PMID 39918986, 2025). "A broad range of CAKUT disorders, including diffuse cystic dysplasia and simple kidney cysts are all reported manifestations of HNF1B-associated kidney disease." (PMID 38676761, 2024). "In this report, we present seven cases of HNF1B-associated kidney disease, each featuring distinct genetic abnormalities and displaying diverse extrarenal manifestations." (PMID 38674137, 2024). "HNF1A and HNF1B are two transcription factors that are closely associated with kidney disease, and both of these transcription factors showed decreased activity in proximal tubule cells with LOY." (PMID 38287344, 2024). "HNF1B and many of its targets are known to cause inherited kidney disease, including CAKUT, and cystic dysplastic kidneys." (PMID 36522156, 2023). "The HNF1B gene is mostly associated with kidney disorders, followed by neurodevelopmental disorders." (PMID 36034547, 2022). "Results from this study importantly connect HNF1B to PGC-1α and merit additional research to explore the involvement of PGC-1α in HNF1B associated kidney diseases." (PMID 33022986, 2020). "Heterozygous germline mutations of HNF1B are the most common monogenic cause of developmental kidney disease and are associated with a wide variety of congenital kidney malformations, which ultimately lead to chronic renal disease in the afflicted individuals." (PMID 33051485, 2020). "This was unexpected since patients had been excluded from our study when they were known to display classical phenotypes, particularly renal disease, associated with HNF1B." (PMID 31291970, 2019). "Faecal elastase-1 was low (below the 2.5 percentile of the control cohort) in 18/29 (62%) patients with HNF1B-associated renal disease." (PMID 30094008, 2018). "Faecal elastase-1 was below the 2.5 percentile of the control cohort in 18/29 (62%) patients with HNF1B-associated renal disease." (PMID 30094008, 2018). "The variable expressivity of HNF1β mutations also extends to the type and age of onset of renal disease, which ranges from intrauterine life to middle age." (PMID 29764441, 2018). "The broad phenotypic variability of both diabetic and renal disease probably accounts for underdiagnoses of HNF1β mutations in clinical practice." (PMID 29764441, 2018). "The median age of individuals with HNF1B-associated renal disease was 25 years (IQR 14–44) and 13/29 (45%) were male." (PMID 30094008, 2018). "The cohort of healthy controls used to define the lower limit of the normal range for faecal elastase-1 were older; the median age was 61.7 years (IQR 52.8–66.3) compared to 24.5 years (IQR 14–44) in the individuals with HNF1B-associated renal disease." (PMID 30094008, 2018). "Despite this single genetic aetiology, the phenotype of HNF1B-associated renal disease is very variable." (PMID 30094008, 2018). "The phenotype of HNF1B-associated kidney disease is highly variable." (PMID 38676761, 2024). "Of interest, individuals with HNF1B-associated renal disease are at increased risk of developing PTDM, and analysis of the HNF1B gene mutations might be useful in predicting PTDM in potential renal transplant recipients." (PMID 38674437, 2024). "We have demonstrated that faecal elastase-1 deficiency is common in HNF1B-associated renal disease and exocrine pancreatic dysfunction may be more symptomatic than previously published." (PMID 30094008, 2018). "Obviously, diseases not expected in adulthood—e.g., ARPKD and rare disorders that go along with variable clinical manifestations like HNF1b-associated kidney disease—may also require a molecular genetic diagnosis." (PMID 29623269, 2018).
kidney disease (continued). "To determine whether the phenotype of CRISPR-Cas9-mutated hESC-derived organoids was representative of HNF1B-associated kidney disease, we evaluated organoids generated from hiPSCs derived from a family carrying a heterozygous deletion of exon 9 (HNF1B+/ΔExon9)." (PMID 38788724, 2024). "Here we compared the neurodevelopmental phenotype of 38 patients with HNF1B-associated renal disease due to an intragenic mutation in 18 patients or due to 17q12 deletion in 20 patients to determine whether haploinsufficiency of HNF1B is responsible for the neurodevelopmental phenotype." (PMID 27234567, 2016). "Having acquired the knowledge of HNF1B-related kidney disease in our unborn patients, we found the related literature with descriptions of fetal US and MRI." (PMID 40839116, 2026). "Bantounas and colleagues created an organoid model of +/−HNF1B-kidney disease by differentiation of CRISPR-edited hESCs or HNF1B-patient iPSCs." (PMID 38788724, 2024). "As for a long time HNF1B-related kidney disease was regarded as primarily a physical disease, some papers report NDDs only as a “side note”." (PMID 36969268, 2023). "Given the link between HNF1B and genetic kidney diseases of various manifestations, we explored the expression of genes associated with inherited kidney disease systematically." (PMID 36522156, 2023). "A total of 97 case descriptions of HNF1B-related kidney disease in combination with a NDD on an individual level were available in 29 papers." (PMID 36969268, 2023). "First proposed in the 2015 Kidney Disease: Improving Global Outcomes (KDIGO) consensus report, ADTKD is currently believed to be caused by gene mutations UMOD, REN, MUC1, HNF1B, SEC61A, and DNAJB11." (PMID 36362756, 2022). "A mutation in the HNF1B gene results in MODY5, which is characterized by reduced insulin secretion and usually a renal disease." (PMID 33477506, 2021). "In both UK and French datasets, patients underwent genetic testing based on clinician suspicion of HNF1B-related renal disease and the majority had CAKUT." (PMID 26022541, 2015). "Renal disease is often the earliest or most prominent feature of HNF1B-MODY." (PMID 41009948, 2025). "HNF1B-associated kidney disease can vary in severity, without clear genotype-phenotype correlations." (PMID 38788724, 2024). "We show that both 17q12 microdeletions and microduplications are associated with renal disease and provide evidence that HNF1B is unlikely to be the sole contributor to all associated phenotypes." (PMID 36109160, 2023). "The severity of the HNF1B mutation‐associated kidney disease phenotype had no clear association with the genotype." (PMID 31056860, 2019). "In contrast, mutations in HNF1β are associated with a wide array of clinical phenotypes that can include renal disease, and which are distinguished by the absence of clear genotype-phenotype associations." (PMID 29764441, 2018). "Mutations in the HNF1B cause MODY5 (maturity-onset of diabetes, type 5) that may be accompanied by urinary tract disorders, including renal disease and/or undeveloped/malformed kidneys and atrophic pancreas." (PMID 24386569, 2013). "Among the three cases of unilateral PKD discovered in this study, P45’s case may have been caused by an HNF1B mutation, while P46 and P47 had no gene mutations on the kidney disease panel and P47 had LYZ, FGA, and GLI3 heterozygous mutations on the WES." (PMID 31056860, 2019). "In this sense, the kidney disease: improving global outcomes recommendation that genetic screening should be a mandatory investigation for these patients is appropriate, especially if it is in the context of a panel of genes such as HNF1B, that include other diseases that may phenocopy GS." (PMID 36938092, 2023). "Besides the well-recognized role of HNF1B, among other genes encompassed in the genomic region, LHX1 has been proposed as a possible modifier for earlier onset renal disease." (PMID 39766333, 2024).
kidney disease (continued). "Notably, injured PT DARs were significantly enriched for NF1, HNF1B, and FOS motifs (NF1 P = 1.0 × 10−266; HNF1B P = 1.0 × 10−214; FOS P = 1.0 × 10−204), known regulators of PT identity, suggesting that epigenetic regulation may have implications for the development of kidney disease." (PMID 38287030, 2024).
neurodevelopmental disorder (10 papers, 2016 to 2023). A behavioral and cognitive disorder with onset during the developmental period that involves impaired or aberrant development of intellectual, motor, or social functions. "Percentages of neurodevelopmental disorders (NDD) in studies reporting on NDDs in patients with 17q12 microdeletions and HNF1B mutations." (PMID 36969268, 2023). "This review investigates the association between neurodevelopmental disorders (NDD) and variations of the gene HNF1B." (PMID 36969268, 2023). "Subsequently, 17q12 deletions encompassing HNF1B, but not HNF1B intragenic mutations, have been found to be associated with neurodevelopmental disorders; hence, the HNF1B gene is not involved in the neurodevelopmental phenotype." (PMID 33340339, 2021). "By analyzing the critical 17q12 region gene content, HNF1B may be responsible for the majority of features related to 17q12 microdeletion/microduplication syndromes, including neurodevelopmental disorders, this gene being widely distributed." (PMID 34828266, 2021). "An increase in neurodevelopmental disorders has been observed in individuals harbouring the 17q12 deletion but not in patients with HNF1B coding mutations." (PMID 30021660, 2018). "Thus, the 17q12 deletions but not HNF1B intragenic mutations are associated with neurodevelopmental disorders." (PMID 27234567, 2016).
kidney (8 papers, 2017 to 2024). "Taken together, our findings show that HNF1B haploinsufficiency could result in pancreas hypoplasia in humans due to an altered production of multipotent progenitors." (PMID 34450036, 2021). "Hepatocyte nuclear factor 1β (HNF1β) has been reported to regulate the development of kidney cystogenesis, diabetic nephrotoxicity, etc However, the regulatory mechanism of HNF1β in cisplatin nephrotoxicity is largely unknown." (PMID 33512774, 2021). "Gene Ontology Overview of the deleted genes showed both HNF1B deletions and LHX1 deletions have significant impacts on structural or functional kidney dysfunctions and malformations of the reproductive system." (PMID 39221224, 2024).
adenocarcinoma (6 papers, 2015 to 2025). A common cancer characterized by the presence of malignant glandular cells. "According to our results, HNF-1β can be considered an adenocarcinoma marker while p63/p40 and D2-40 are highly specific markers of SCC with variable sensitivity." (PMID 25884453, 2015). "In our study, we found expression of HNF-1β in 42/56 cases of adenocarcinoma (75%) and in 2 only /85 cases of SCC (2.35%)." (PMID 25884453, 2015). "Dicer1 and PTEN-deficient mice developed endometrial adenocarcinomas that were poorly differentiated and overexpressed the clear-cell adenocarcinoma markers, HNF1B (hepatocyte nuclear factor 1 homeobox B), and napsin A. These adenocarcinomas did not respond to hormones." (PMID 38836981, 2024). "Adenocarcinomas showed expression of HNF-1β in 42/56 cases (75%), CEA in 48/56 cases (85.7%), p63 in 4/56 cases (7.2%), p40 in 2/56 cases (3.6%), estrogen receptors in 9/56 cases (16.1%), progesterone receptors in 5/56 cases (8.9%), p16 in 56/56 (100%) cases, and D2-40 in 0/56 cases (0%)." (PMID 25884453, 2015).